SEC23B (SEC23 homolog B, COPII component)
Description:
Component of the coat protein complex II (COPII) which promotes the formation of transport vesicles from the endoplasmic reticulum (ER). The coat has two main functions, the physical deformation of the endoplasmic reticulum membrane into vesicles and the selection of cargo molecules for their transport to the Golgi complex.
Synonyms: hSec23B; CDA-II; CDAII; HEMPAS; CDAN2; CWS7
Tractability: Antibody: UniProt places it where antibodies can reach, with medium confidence. PROTAC: ubiquitination databases record sites on it; its protein half-life has been measured.
Gene: Protein-coding gene on chromosome 20 (18,507,520 to 18,561,415, forward strand). Ensembl gene ENSG00000101310.
Subcellular location: Cytoplasmic vesicle, COPII-coated vesicle membrane; Endoplasmic reticulum membrane; Cytoplasm, cytosol
Subcellular location (Human Protein Atlas): Cytosol; Endoplasmic reticulum; Vesicles
Gene Ontology:
Molecular function: protein binding; GTPase activator activity; zinc ion binding
Biological process: COPII-coated vesicle cargo loading; COPII-coated vesicle budding; endoplasmic reticulum to Golgi vesicle-mediated transport; intracellular protein transport
Cellular component: endomembrane system; endoplasmic reticulum; endoplasmic reticulum membrane; COPII vesicle coat; cytosol; ER to Golgi transport vesicle membrane; perinuclear region of cytoplasm
Genetic constraint (gnomAD): Loss-of-function variants: 65 observed, 79.3 expected, observed/expected ratio (o/e) 0.82, 90% interval 0.67 to 1.01. The upper end of that interval is the gene's LOEUF score, 1.01, which puts it in group 4 of 6, group 1 being the genes least tolerant of losing a copy. Missense variants: 741 observed, 840.39 expected, observed/expected ratio (o/e) 0.88, 90% interval 0.83 to 0.94. Synonymous variants: 301 observed, 304.31 expected, observed/expected ratio (o/e) 0.99, 90% interval 0.9 to 1.09.
Gene-disease validity (ClinGen):
ClinGen rates the evidence that SEC23B causes each of these diseases.
congenital dyserythropoietic anemia type 2 (autosomal recessive): Definitive. Congenital dyserythropoietic anemia type II (CDA II) is the most common form of CDA characterized by anemia, jaundice and splenomegaly and often leading to liver iron overload and gallstones.
Homologues: Orthologues: chimpanzee SEC23B (99% identical), macaque SEC23B (99% identical), dog SEC23B (98% identical), pig SEC23B (98% identical), mouse Sec23b (97% identical), rat Sec23b (97% identical), rabbit SEC23B (97% identical), guinea pig SEC23B (94% identical), tropical clawed frog sec23b (92% identical), zebrafish sec23b (86% identical), Drosophila melanogaster Sec23 (74% identical), Caenorhabditis elegans sec-23 (60% identical). Paralogues in human: SEC23A (85% identical).